TM4SF1 (transmembrane 4 L six family member 1)
Diseases named in the same sentence as TM4SF1 in open-access papers (continued):
Sharing a sentence is not in itself a finding about the gene and the disease.
tumor (continued). "In our tumor epithelial dataset, genes with the strongest positive correlation with TM4SF1 expression within the HV tumor cells were EMP1, CLDN4, EZR, and KRT19." (PMID 40527915, 2025). "In tumor cells, others have demonstrated that TM4SF1 interacts with membrane proteins like genuine tetraspanins (CD81, CD151, CD63, and CD13) and signaling proteins like DVL2, SITAC, and DDR1." (PMID 41226530, 2025). "To validate the specificity of our CARs, we used CRISPR/Cas9 to generate TM4SF1 knockouts (KO) in the UMUC3 cell line, which eliminated the surface expression of TM4SF1 protein and impaired the anti-tumor activity of TM4SF1-CAR T cells." (PMID 40527915, 2025). "Most HV tumor clusters, including Cluster 13, exhibited higher expression of TM4SF1 compared to tumor clusters from pure UC tumors." (PMID 40527915, 2025). "In Tm4sf1 wild type mice, mean tumor volumes were 152.4 ± 28.3 mm3 at day‐6 and 1855 ± 475.6 mm3 at day‐12, after which mice had to be sacrificed." (PMID 38946725, 2024). "Quantitative analysis of the Western blot data visually confirmed the differential expression patterns observed, with higher levels of SCD, SUMF2, and KDEL2R in tumor tissues, and higher levels of TM4SF1 in paracancerous tissues." (PMID 39104534, 2024). "In contrast, mean tumor volumes in Tm4sf1‐heterozygous mice were 63.1 ± 14.2 mm3 at day‐6 and 297 ± 51.9 mm3 at day‐12, and tumors ultimately reached a size of 1472 ± 200.9 mm3 on day‐25." (PMID 38946725, 2024). "B16F10 tumor growth was substantially delayed in Tm4sf1‐heterozygous mice, requiring two weeks longer than in wild‐type mice to grow to 10% of body weight." (PMID 38946725, 2024). "In this study, we investigated the ability of live‐born Tm4sf1‐heterozygous mice to manage angiogenesis in the challenges of tumor growth and wound healing." (PMID 38946725, 2024). "In this study, we first investigated TM4SF1's ability to support pathological angiogenesis for tumor growth and wound healing in Tm4sf1‐heterozygous mice." (PMID 38946725, 2024). "The results showed that the expression of TM4SF1 and stem-related molecules in primary tumor cells of nude mice increased." (PMID 37069693, 2023). "The results showed that the expression of Notch pathway related molecules decreased in primary tumor cells of nude mice silenced with TM4SF1." (PMID 37069693, 2023). "The results showed that the size and number of tumor spheres formed by TM4SF1-silenced HCC cells were inferior to those in the control group." (PMID 37069693, 2023). "miR-141-3p and miR-141-5p exercise their tumor suppressor function by targeting transmembrane-4-L-six-family-1 (TM4SF1), a small 22-kDa four-transmembrane-domain protein, determining an inhibition of cell migration and invasion of PC cells." (PMID 37273899, 2023). "Expression of LIF was higher in TM4SF1+ tumor cells and proliferative tumor cells, particularly in advanced CRC tissues." (PMID 37360193, 2023). "Collectively, high TM4SF1 expression found in HCC cells and tumor-associated HUVEC allude to its potential as a dual therapeutic target." (PMID 36678607, 2023). "In contrast, Zheng, Ohuchida found that patients with low levels of TM4SF1 in PC tissues had higher tumor grade, advanced clinical stages, and shorter survival periods than patients with higher levels of TM4SF1." (PMID 36678607, 2023). "We extracted RNA from the tumor spheres, and through qPCR test, we found that the expression of TM4SF1 in the tumor spheres formed by LM3-LR was abnormally increased compared with the untreated group." (PMID 37069693, 2023). "TM4SF1 expression was markedly higher in CRC tissues than in non-tumor tissues and was positively correlated with poor prognosis." (PMID 36816947, 2023).
tumor (continued). "TM4SF1 expression was found to be markedly enhanced in tumor tissues relative to normal controls via immunohistochemistry, and this was confirmed via qPCR." (PMID 35730016, 2022). "In detail, the expressions of TM4SF1 were strongly upregulated in ESCC tissues than in non-tumor tissues at both mRNA and protein levels." (PMID 35835740, 2022). "In tumor xenograft tissue, the frequency of Ki-67+ cells was significantly reduced following the TM4SF1 overexpression, whereas TUNEL staining was increased." (PMID 35153775, 2022). "In primary pancreatic ductal adenocarcinomas (PDAC), TM4SF1+ tumor cells had mutually exclusive spatial locations with S100A4+ tumor cells." (PMID 36313703, 2022). "Overall, our data show that BCYRN1 can enhance TM4SF1 expression in a BATF recruitment-dependent fashion to modulate tumor malignancy, thereby enhancing HCC cell migration, invasion, and proliferation." (PMID 35730016, 2022). "Transmembrane-4 L-six family member-1 (TM4SF1) is a member of the L6 family and functions as a signal transducer to regulate tumor cell behaviors." (PMID 35835740, 2022). "Transmembrane 4 L Six Family Member 1 (TM4SF1) is related to tumor metastasis and regulates angiogenesis, making it a potential target for anti‐angiogenesis and anti‐tumor therapy." (PMID 34995016, 2022). "Our results indicate that TM4SF1/integrin α6/FAK axis is positively correlated with tumor progression and poor prognosis and has the potential to serve as a prognostic factor and therapeutic target in ESCC." (PMID 35835740, 2022). "In line with our above results, BCYRN1 and BATF overexpression accelerated tumor growth, whereas TM4SF1 silencing had the opposite effect." (PMID 35730016, 2022). "DEG analysis after chemotherapy showed only moderate transitions whilst tumor-associated DEGs included ACKR1, RGCC and TM4SF1." (PMID 36253784, 2022). "Downregulation of TM4SF1 inhibited the migration, invasion and tumour sphere formation of SW480 and LoVo cells." (PMID 33153498, 2020). "These genes were distributed in multiple pathways, and some of them, such as MET (ranked 1st), PRKDC (ranked 8th), EXO1 (ranked 14th), and TM4SF1 (ranked 25th), have been reported to promote tumor cell proliferation." (PMID 32995120, 2020). "TM4SF1 expression was markedly higher in CRC tissues than in non-tumour tissues and was positively correlated with poor prognosis." (PMID 33153498, 2020). "In general, most previous studies have focused on the role of TM4SF1 in regulating tumor invasion and metastasis." (PMID 31142317, 2019). "RT-PCR was further used to confirm the TM4SF1 expression in five pairs of lung tumor tissues and non-tumor tissues." (PMID 31142317, 2019). "Many researchers have implemented targeted antibody therapy, antibody-directed enzyme prodrug therapy, radioimmunotherapy, and targeted therapy with conjugated anti-tumor drugs directly targeting TM4SF1." (PMID 30876464, 2019). "Transmembrane-4 L-six family member-1 (TM4SF1), an antigen that serves as an oncogene, mainly affects tumor invasion and metastasis." (PMID 31142317, 2019). "Immunization with the cytotoxic T lymphocyte (CTL) epitope of TM4SF1 in HLA-A2 transgenic mice induced CTL immune responses to effectively inhibit the growth of tumor cells that expressed TM4SF1." (PMID 30876464, 2019). "Immunofluorescence microscopy also demonstrated that TM4SF1 deposits in the cytoplasm, and tentatively in nuclei of both cultured endothelial cells and tumor cells." (PMID 29665316, 2018). "TM4SF1 is a tumor suppressor for GC and a novel prognostic marker for patients with GC, where the exact role of TM4SF1 remains and deserves further investigation." (PMID 29665316, 2018). "Four weeks after injection, tumor xenografts were collected and detected of TM4SF1 expression level." (PMID 27974706, 2017).
tumor (continued). "TM4SF1 was down-regulted in lenti-miR-141 cells, and weight measurement showed that tumor xenografts from lenti-miR-141 cells were much lighter than those from KYSE150 and lenti-miR-NC." (PMID 27974706, 2017). "HepG2 cells overexpressing TM4SF1 showed reduced apoptosis and increased cell migration in vitro and enhanced tumor growth and metastasis in vivo, whereas siRNA-mediated silencing of TM4SF1 had the opposite effect." (PMID 27153056, 2016). "Several researches showed that TM4SF1 was overexpressed in human tumor vascular endothelial cells and TM4SF1-antibody was selectively targeted to tumor blood vessel endothelial cells and tumor cells with little toxicity." (PMID 26709920, 2015). "We provide evidence that ARHGDIA, COBLL1, and TM4SF1 are negative regulators of apoptosis in cultured tumor cells." (PMID 21569526, 2011). "However, overexpression of the C79A+C88A double mutants displayed significantly impaired TM4SF1 palmitoylation in 4T1 and EMT6.5 tumor spheroids silenced for wildtype Tm4sf1." (PMID 41826695, 2026). "TM4SF1 is an integral membrane protein that internalizes from the cell surface along microtubules to the nucleus and is highly expressed on the surface of both tumor endothelium and tumor cells." (PMID 42196417, 2026). "Furthermore, TM4SF1 knockdown reduced cell proliferation, invasion, and migration, along with tumor growth in vivo and in vitro." (PMID 42305440, 2026). "During the treatment process, the risk of MVI in patients is assessed preoperatively by deTECsting the TM4SF1 expression level, so as to develop a more precise surgical plan; in the postoperative period, the use of TM4SF1 inhibitors can prevent tumor recurrence." (PMID 40123905, 2025). "We also find enriched expression of TM4SF1, a transmembrane protein, in HV tumor cells." (PMID 40527915, 2025). "We report here that tumor growth and wound healing are inhibited in Tm4sf1‐heterozygous mice." (PMID 38946725, 2024). "We now report (i) inhibition of B16F10 tumor growth and wound healing in Tm4sf1‐heterozygous mice, and (ii) that 12 out of 18 signaling molecules examined are recruited to TMED on the cell surface and 10 were found to internalize with TMED; PLCγ and HDAC6 notable among them." (PMID 38946725, 2024). "TM4SF1 has been extensively cited in prior research as a facilitator of tumor growth." (PMID 38762481, 2024). "Whether any paracrine mechanism exists in which the reduced TM4SF1 levels in the endothelium of TM4SF1 heterozygotes can influence TM4SF1 expression in tumor cells and consequently affect tumor growth indirectly is currently unknown." (PMID 38946725, 2024). "Conversely, TM4SF1 expression was higher in paracancerous tissues than in tumor tissues." (PMID 39104534, 2024). "Additionally, Cao, Wang also reported that TM4SF1 silencing using shRNA in vitro and in vivo distinctively inhibited cell and tissue proliferation and tumor growth." (PMID 36678607, 2023). "TM4SF1 silencing also led to the reduction of tumor size in gemcitabine-based treatment in vivo." (PMID 36678607, 2023). "TM4SF1 also could increase tumor growth and metastasis in a murine model in which these effects were reversed after TM4SF1 silencing." (PMID 36678607, 2023). "In PRC progression, the AR pathway activation leads to tumor overgrowth; thus, TM4SF1 could be a target gene or potential biomarker for PRC in therapeutic strategies." (PMID 36678607, 2023). "Next, we examined the effect of TM4SF1 on tumor metastasis in a mouse lung colonization model." (PMID 35835740, 2022). "Moreover, TM4SF1 exhibited a lower expression along with the tumor stage and lower in lymph node–positive tissue specimens than that in lymph node–negative tissue specimens." (PMID 35153775, 2022). "It is well known that laminin plays essential roles in multiple tumor biological functions, so we questioned whether laminin was also involved in regulating TM4SF1 in cell proliferation and migration." (PMID 35835740, 2022).
tumor (continued). "Moreover, TM4SF1 regulated endothelial cell functions, including filopodia formation, cell mobility, cytokinesis, cellular senescence, and tumor angiogenesis." (PMID 33958586, 2021). "TM4SF1 was shown to enhance the expression of Yes-associated protein (YAP) and strengthened YAP-transcriptional enhancer activator domain (TEAD) interaction to regulate the progression of malignant tumor cells." (PMID 33015133, 2020). "A previous study reported that TM4SF1 was also upregulated in endothelial cells lining angiogenic tumour blood vessels, and they also found that TM4SF1 serves as a molecular organizer that is essential for the formation of nanopodia and the maturation of angiogenesis." (PMID 33153498, 2020). "Peptide 5 is a TM4SF1 CTL (cytotoxic CD8 T-cell) epitope and may induce T-cell reactions after DNA immunization and increase peptide-specific cytotoxic T cells (CD107a+, CD8+), thus inhibiting the growth of EL4/TM4SF1/HLA-A2 tumor cells in A2 Tg mice." (PMID 33015133, 2020). "In addition, high TM4SF1 expression was significantly correlated with tumour T stage and lymph node metastasis (P < 0.01) but not with age, sex, tumour size, or tumour differentiation (P > 0.05)." (PMID 33153498, 2020). "Furthermore, the effect of TM4SF1 on tumour metastasis was examined by using mouse tail-vein injection model." (PMID 33153498, 2020). "TM4SF1 knockdown markedly suppressed tumour growth in vivo compared to that of the controls." (PMID 33153498, 2020). "The influence of TM4SF1 on tumor cell proliferation suggested that it may induce cell apoptosis resistance in NSCLC cell lines." (PMID 31142317, 2019). "TM4SF1 is expressed abundantly on many cancer cells, on tumor blood vessel endothelial cells." (PMID 31140150, 2019). "However, the nude mice tumor formation experiment showed that inhibition of TM4SF1 expression in HO8910PM cells significantly inhibited the growth of xenograft tumors." (PMID 30876464, 2019). "Additionally, TM4SF1 has been reported to be an oncogene promoting tumor cell invasion metastasis, tumor angiogenesis, and the progression of multiple cancers." (PMID 31142317, 2019). "Studies have found TM4SF1 participates in regulating tumor cell invasion and migration." (PMID 30876464, 2019). "TM4SF1 was first discovered as a tumor cell antigen and could be specifically recognized by mouse monoclonal antibody L6." (PMID 31140150, 2019). "TM4SF1 is a tumor suppressor for GC and a novel prognostic marker for patients with GC." (PMID 29665316, 2018). "The results suggested that TM4SF1 was a tumor suppressor in GC progression and invasion." (PMID 29665316, 2018). "This yielded 88 genes associated with tumor grade, in which seven DEGs (C8orf33, TSNAXIP1, TM4SF1, CTH, ANXA2, KIAA1522 and LRRC1) can distinguish HCC of G3 from G1, two DEGs (CYB5A and RRAGD) can distinguish HCC of G3 from G2, and two DEGs (CFHR4 and F13B) can distinguish HCC of G3 from G4." (PMID 29123978, 2017). "Importantly, recently study has shown that TM4SF1-targeting Antibody Drug Conjugates represent a promising therapeutic agent against tumor cells and the tumor vasculature." (PMID 26709920, 2015). "We conducted a high-throughput RNA inhibition screen to knockdown gene expression levels of the four genes comprising the test (ARHGDIA, COBLL1, PKM2, TM4SF1) in both a human lung-derived normal and a tumor cell line using three different small inhibitory RNA molecules per gene." (PMID 21569526, 2011). "The changes in TM4SF1 expression during the developmental process of TECs3 might play a crucial role in modulating the function of endothelial cells and their interaction with tumor cells, thereby influencing the occurrence and progression of MVI in HCC." (PMID 40123905, 2025). "Thus, tumor volumes in wild type mice were 2.42‐fold (day‐6; p = 0.000003 Student's t‐test) and 6.25‐fold (day‐12; p = 0.000012, Student's t‐test) higher than in Tm4sf1‐heterozygous mice; similar results were obtained in both male and female mice." (PMID 38946725, 2024).
tumor (continued). "Finally, depletion of TM4SF1 inhibited metastasis and tumour growth in a xenograft mouse model." (PMID 33153498, 2020). "Furthermore, DDR1 has been reported to interact with TM4SF1 and to induce tumor metastasis." (PMID 31142317, 2019). "Therefore, we concluded that Tm4sf1 and Csf1 found to be overexpressed in lung TCs may have a role in tumour promotion." (PMID 25278030, 2014). "The spatial enrichment of TM4SF1 expression and of TECs3 as a proportion of the total endothelial cell content were analyzed in control (HCCN), tumor peripheral (HCCL), central tumor (HCCT) and PVTT tumor (HCCP) tissues." (PMID 40123905, 2025). "In vitro experiments demonstrated that CAR-T cells can specifically eliminate TM4SF1-positive tumor cell lines, while in vivo studies revealed that these modified immune cells significantly inhibited SKOV3-derived tumor growth." (PMID 38903506, 2024). "The co‐expression of any 1 gene from Group A (C19orf33, S100A14, and RHOD; count ≥1) and any 1 gene from Group B (CST6, CD44, TM4SF1, and TACSTD2; count ≥1) in a single tumor cell was defined as a MIC." (PMID 38864342, 2024). "Here our study, for the first time, provides the evidence that TM4SF1 is positively correlated with TNM stage, N classification, differentiation, tumor size, and poor outcome." (PMID 35835740, 2022). "The immunohistochemistry results suggested that the expression of TM4SF1, FASN, and IMPDH1 was significantly elevated in tumor tissue specimens, while the expression of KCNK5 and KCNJ15 was downregulated." (PMID 35480865, 2022). "Here, we find that TM4SF1 expression is increased and positively correlated with clinical TNM stage, N classification, differentiation, tumor size, and poor prognosis in ESCC patients." (PMID 35835740, 2022). "From a mechanistic perspective, BATF was recruited to the TM4SF1 promoter by BCYRN1, and reducing the expression of this lncRNA was sufficient to constrain xenograft tumor growth in mice." (PMID 35730016, 2022). "A conjugate consisting of 2A7A, a humanized TM4SF1 mAb, and the auristatin cytotoxic agent LP2 (chemical name mc-3377) damaged the ECs in the mouse tumor vasculature and inhibited the growth of several tumor xenografts with dosage-related toxicity." (PMID 33015133, 2020). "To validate the function of endogenous TM4SF1 in vivo, we constructed stably transfected SW480 cells, subcutaneously injected them into BALB/c-nu mice and then measured tumour growth in the xenograft mouse model weekly." (PMID 33153498, 2020). "Oral submucous fibrosis (OSF) is a potentially malignant tumor, and in OSF, miR-203 promotes EMT by targeting TM4SF1 and downregulating the expression of CK19 and E-cadherin while upregulating the expression of N-cadherin and vimentin." (PMID 33015133, 2020). "To date, many tumor metastasis- and invasion-related studies have focused on CD9, CD81, CD82/KAI1, CD151, and TM4SF1." (PMID 30876464, 2019). "The results showed that there was an obvious positive correlation between TM4SF1 and DDR1 mRNA expression in tumor tissue samples." (PMID 28368050, 2017). "Knockdown of ARHGDIA, COBLL1, and TM4SF1 resulted in 2- to 4-fold increased levels of apoptosis in normal cells (ARHGDIA only) and tumor cells (all three genes)." (PMID 21569526, 2011). "Moreover, plasma membrane localization of the TM4SF1 C79A+C88A double mutants greatly decreased compared to wildtype overexpression in 4T1 and EMT6.5 tumor spheroids silenced for wildtype Tm4sf1." (PMID 41826695, 2026). "In line, overexpression of wildtype Tm4sf1 in Zdhhc20 silenced 4T1 tumor spheroids failed to rescue STAT3 phosphorylation, KAT2A gene and protein expression in the presence and absence of extra palmitate." (PMID 41826695, 2026). "TM4SF1’s high expression in proliferating endothelial cells and tumor cells of solid tumor origin, and low or no expression in most other cell types, positions TM4SF1 as an attractive target for solid tumor treatment." (PMID 41226530, 2025).